ERBB2 (erb-b2 receptor tyrosine kinase 2)
Diseases named in the same sentence as ERBB2 in open-access papers (continued):
Sharing a sentence is not in itself a finding about the gene and the disease.
breast cancer (continued). "In fact, up to one quarter of women with breast cancer are ErbB2 positive and are therefore eligible for treatment with anthracycline–trastuzumab, which is associated to a higher rate (28%) of heart failure." (PMID 32414364, 2020). "Targeted monotherapies are ineffective in the treatment of brain metastasis of ERBB2+ breast cancer (BC) underscoring the need for combination therapies." (PMID 33019652, 2020). "A high fatty acid synthase (FASN) activity is also involved in ErbB2-induced breast cancer chemoresistance to docetaxel." (PMID 32211323, 2020). "Invasion of the MCF7 breast cancer spheroids expressing the trastuzumab-resistant p95 form of ErbB2 depends on the activation of a signaling network that culminates in the activation of MZF1." (PMID 31963147, 2020). "ErbB2 breast cancer still remains an unmet need due to primary and/or acquired resistance to current treatment strategies." (PMID 32695336, 2020). "A hyperactive PI3K/AKT/mTOR pathway is a characteristic of up to 70% of breast cancers of all molecular breast cancer subtypes, i.e., Luminal A, Luminal B, Her2 (ErbB2)-enriched, as well as basal-like, triple-negative cancers." (PMID 32707827, 2020). "Celastrol signifcantly retarded the rate of growth of ErbB2-overexpressing human breast cancer cells in vivo with only minor systemic toxicity." (PMID 33364939, 2020). "In conclusion, liposomes targeting ErbB2 have the potential to be an efficient drug delivery carrier for treating ErbB2-positive breast cancer." (PMID 32599712, 2020). "ERBB2/HER2: We examined the ERRB2/HER2 gene as it is a common biomarker used to assess patients with breast cancer (Birnbaum, Sircoulomb & Imbert, 2009)." (PMID 33062421, 2020). "MEDICA effects were further verified by growth suppression of trastuzumab-sensitive and trastuzumab-resistant AU565 and BT474 human ErbB2 breast cancer cells." (PMID 32695336, 2020). "Here we report a successful microscaled proteogenomics demonstration project in patients with ERBB2 + breast cancer." (PMID 31988290, 2020). "Using the CCLE data, a gene-centric integration in each cluster accurately identified known drivers in several cancer types, including MITF in melanoma, ERBB2 in breast cancer, EGFR and MET in LUAD, and MYCN in brain tumors." (PMID 32076369, 2020). "For example, while HTT regulates the normal development of the mammary tissue, mutant HTT expression is pro-metastatic in breast cancer and can accelerate tumor development through ErbB2/HER2 signaling." (PMID 32295075, 2020). "Although adjuvant trastuzumab has been the standard of care for ERBB2-positive early breast cancer since 2006, its optimum duration has been uncertain." (PMID 32833018, 2020). "In breast cancer, ligation of integrin α3β1 with laminins protected tumor cells from anti-ErbB-2 agents via activation of the MAPK pathway." (PMID 32232000, 2020). "Cicalese and coworkers, while using a ERBB2 trasngenic model of breast cancer, showed that the self-renewing of cancer stem cells is higher that that observed at the level of normal mammary stem cells." (PMID 32210163, 2020). "miR-125a-5p can decrease the proliferation of breast cancer cells by interfering with ERBB2 protein expression." (PMID 32427576, 2020). "Particularly, it has been shown that ERBB2 over-expression boosts invasion and metastasis of breast cancer and is correlated with poor survival of patients." (PMID 33381459, 2020). "Here, we present a case report of pneumonitis as a rare side effect of palbociclib in the treatment of metastatic hormone receptor-positive (HR+)/human epidermal growth factor receptor 2-negative (ERBB2-) breast cancer in addition to endocrine therapy." (PMID 32760629, 2020).
breast cancer (continued). "Breast cancer cells characteristic of the ErbB2+/luminal (NIC) or basal (4T1) subtypes were engineered to overexpress p66ShcA." (PMID 31941526, 2020). "Our findings indicate that miR-125a-3p is capable of inducing a shift in the involvement of the ErbB2 pathway in the basal-like subtype of breast cancer, thereby sensitizing the cells to anti-HER2 therapies." (PMID 32185126, 2020). "T-DM1 along with either tucatinib, palbociclib or afatinib is being investigated in advanced ErbB2-positive breast cancer patients (NCT03975647, NCT03560696, and NCT04158947)." (PMID 33081383, 2020). "To determine the impact of p66ShcA on breast cancer metastasis, we chose established models of ErbB2+/Luminal (NIC) and triple-negative (4T1) disease." (PMID 31941526, 2020). "Receptor tyrosine-protein kinase ERBB2 (HER2) expression is most well-known for its role in a subset of breast cancers; however, HER2 expression is seen in approximately 40% of medulloblastomas." (PMID 32903405, 2020). "Evaluating the indicated proteins as potential biomarkers of metastatic ErbB2-positive breast cancer response to trastuzumab-based therapies in a large patient cohort represents an important future direction of our research." (PMID 33023655, 2020). "In spite of the advances accomplished in treating ErbB2 breast cancer, the ErbB2 cancer challenge still remains an unmet need." (PMID 32695336, 2020). "Currently, the dual IGF1/2-neutralizing antibody xentuzumab in combination with everolimus and exemestane is subject to clinical trial in ER+/ErbB2- breast cancer." (PMID 32493414, 2020). "In conclusion, the ephrinB1/ERBB2 (in breast cancer) and ephrinB1/ERBB1 (in head and neck cancer) complexes induce MAPK pathway activation and are positively regulated by SRC and negatively regulated by PTPN13." (PMID 33322542, 2020). "ErbB2/HER2 oncoprotein often drives breast cancers (BCs) which are treated with the anti-ErbB2 antibody trastuzumab." (PMID 33023655, 2020). "According to gene expression profiles, breast cancer is classified into four major subtypes: luminal A, luminal B, ERBB2-enriched (also called HER2-enriched), and basal-like (also called triple-negative breast cancer – TNBC)." (PMID 32448168, 2020). "Three molecular markers, ER, PR and ERBB2, used for breast cancer typing were also used for grouping." (PMID 32967061, 2020). "In breast cancer, let-7e negatively regulates Myeloid Zinc Finger 1 (MZF1), a transcription factor that ultimately upregulates lysosomal cathepsins B and L in the context of ErbB2 positive breast cancer." (PMID 33066614, 2020). "In this case, we have developed a highly specific ErbB2-targeting drug delivery system for maximizing the therapeutic efficiency of Rapa in ErbB2-positive breast cancer." (PMID 32599712, 2020). "A key signaling nexus in breast cancer is the receptor tyrosine kinase HER2, also called ERBB2, which is upregulated in 25% of breast cancer cases and promotes metastasis, partially by activating HSF1." (PMID 32408596, 2020). "Among our four defined breast cancer subtypes, the ERBB2-, ER/PR+ subtype showed the best MFS, whereas the ERBB2+, ER/PR- subtype had the worst prognosis." (PMID 32448168, 2020). "In a recent study that utilized ErbB2 positive breast cancer cells for phosphorylation analysis by Mass Spectrometry, 13 MZF1 phosphorylation sites were identified." (PMID 31963147, 2020).
breast cancer (continued). "Herein, a simple electrochemical immunosensor is developed with an integrated electrochemical probe on the sensing surface, which is able to sensitively and reagentlessly detect the breast cancer biomarker, human epidermal growth factor receptor 2 (ErbB2)." (PMID 35514560, 2020). "The aim of DP1 was to investigate the feasibility of proteogenomic profiling in core biopsies from patients with locally advanced ERBB2 + breast cancer." (PMID 31988290, 2020). "Suppression of ErbB2 breast cancer by MEDICA in vivo was further verified in nude mice xenografted with immortalized RH2111 ErbB2/neu cells derived from breast tumors of the FVB MMTV-ErbB2/neu transgene." (PMID 32695336, 2020). "Activation and overexpression of epidermal growth factor receptor (EGFR, also known as ErbB) family members, including EGFR (ErbB1 or HER1), HER3 (ErbB3), HER4 (ErbB4), and HER2 (ErbB2), govern multiple important cellular processes in breast cancer." (PMID 32223744, 2020). "In a study, HSV1-tk gene under ERBB2 251 bp promoter (p256-TK) transcriptional control was transfected in breast cancer cells, resulting in a higher ganciclovir sensibility without affecting normal cells." (PMID 33381459, 2020). "For ERBB2-positive breast cancer, there are several neoadjuvant chemotherapy options, each associated with different costs, toxic effects, and rates of pCR." (PMID 33226431, 2020). "Identification of the deregulated ERBB2 pathway in breast cancer pathogenesis has led to the development of ERBB2 targeted therapies." (PMID 33381459, 2020). "In this study, we designed peptide-conjugated liposomes specifically targeting ErbB2-positive BT-474 breast cancer cells." (PMID 32599712, 2020). "In our experiments, hypoxia changed the phenotype of all investigated cell lines to an EGFR/ErbB-2 double-positive phenotype, which characterizes aggressive breast cancers." (PMID 32466213, 2020). "In this work, we demonstrate an electrochemical immunosensor with surface-confined electrochemical probe for sensitive and reagentless detection of breast cancer biomarker ErbB2." (PMID 35514560, 2020). "ErBb2, also known as Human epidermal growth factor receptor 2 (HER2), is highly expressed in 15–20% of breast cancers." (PMID 32722184, 2020). "Breast cancer molecular subtypes, i.e., based on the estrogen receptor (ER), progesterone receptor (PR) and receptor tyrosine-protein kinase erbB-2 (HER2) expression profiles, have helped in unraveling the heterogeneity nature of the disease." (PMID 32458655, 2020). "On the other hand, there are studies indicating that up-regulation of miR-205-5p in breast cancer cells suppressed the expression of ErbB2 and induced resistance to targeted therapy." (PMID 33324567, 2020). "(A) Representative zoom-in chromosome views of clonal prototypical breast cancer amplicons such as ERBB2 and CCND1 identified in patient samples." (PMID 32401198, 2020). "ML364 potentiates the pro-degradation effects of HSP90 inhibitors on ErbB2 and hence sensitizes ErbB2-positive breast cancer cells to HSP90 inhibition." (PMID 32327714, 2020). "The small sample of American Indian and Alaska Native women did not allow for including this population in Joinpoint analysis, and the small sample of women diagnosed with ERBB2-enriched breast cancer subtype resulted in imprecise estimates." (PMID 32804214, 2020). "These considerations prompted our interest to study MEDICA activity in the ErbB2 breast cancer context." (PMID 32695336, 2020). "This comprehensive dataset included many established biomarkers for breast cancer, including the receptor tyrosine kinase erbB-2 (HER2), estrogen receptor (ESR1), progesterone receptor (PGR), and androgen receptor (AR)." (PMID 32489334, 2020).
breast cancer (continued). "The shift from glycolysis to OxPhos has also been showed upon MYC/KRAS or MYC/ERBB2 removal in breast cancer cells, and also in glioma cells because of the acquired resistance to phosphoinositide-3-kinase (PI3K)." (PMID 32211323, 2020). "Next, we compared BRF2 overall survival status results with known oncogenes and biomarkers in breast cancer by analyzing the same data set for ERBB2 (HER2), ESR1 (ER), and PIK3CA." (PMID 33176745, 2020). "Taken together, our findings unveil USP2 as a guardian of ErbB2 abundance in ErbB2-positive breast cancers, with its DUB activity required to antagonize the endocytic degradation of ErbB2 under steady state conditions." (PMID 32327714, 2020). "Let-7 binds to the 3′-untranslated region of MZF1, and ectopic expression of let-7 microRNAs let-7d and let-7e can efficiently downregulate MZF1 and invasion of constitutively active ErbB2-expressing breast cancer cells." (PMID 31963147, 2020). "Suppression of ErbB2 breast cancer by MEDICA was corroborated by suppressing ErbB2/neu xenografts in NOD/SCID mice." (PMID 32695336, 2020). "erbB2 (Her2/Neu) is a proto-oncogene that is amplified/overexpressed in approximately 30% of breast cancer cases." (PMID 32353937, 2020). "In most HER2 (ERBB2)-positive breast cancers, there is a significant correlation between CDK12 overexpression and tumor aggressiveness." (PMID 32451425, 2020). "What is the cost-effective neoadjuvant-adjuvant treatment strategy among several clinically reasonable alternatives for human ERBB2-positive breast cancer in the United States?" (PMID 33226431, 2020). "In the present study, we identify two convergent AS regulatory pathways (ZRANB2 and SYF2 splicing factors converging on ECT2 splicing) that control resistance to Doxo in breast cancer, specifically in ER+ERBB2- tumors (the main subtype of breast cancer)." (PMID 31943118, 2020). "Conditional knockout mice showed that Hk2 was required for tumor initiation and maintenance in Kras-driven lung cancer and Erbb2-driven breast cancer." (PMID 33052246, 2020). "Many clinical studies targeting ErbB2 have been actively carried out to date and the effectiveness of this approach in ErbB2-positive breast cancer has been demonstrated." (PMID 32599712, 2020). "To develop novel ErbB2-targeting strategies, we investigated the endocytic degradation and reversible ubiquitylation of ErbB2 in breast cancer." (PMID 32327714, 2020). "Previous studies have indicated that patients with triple-negative breast cancer have worse clinical outcomes compared with hormone-receptor-positive (ER+ and PR+) and ERBB2-positive (ERBB2+) breast cancer patients." (PMID 32164337, 2020). "Breast cancer is classified to luminal, basal-like, ERBB2, and normal breast-like subtypes, in which basal-like tumors show the highest degree of malignancy, the poorest outcomes and the lowest rate of 5-year survival." (PMID 32792858, 2020). "Human HER2+ breast cancer cells are redirected to adopt a normal mammary epithelial phenotype in a similar fashion as erbB2+ mouse mammary cancer cells, human TNBC cells, and human testicular embryonal carcinoma cells in vivo." (PMID 32774772, 2020). "ERBB2 β3‐αC deletions (ΔLRENT) were only detected in breast cancers, which were sensitive to EGFR/ERBB2 inhibitor neratinib and resistant to lapatinib." (PMID 32757330, 2020). "Currently, trastuzumab, in combination with chemotherapy,is considered the main drug for ErbB2-positive breast cancer." (PMID 32742732, 2020). "The ability of THC to treat ErbB2-positive breast cancer, a very aggressive form of cancer has been evaluated." (PMID 32708138, 2020). "CTC‐ITB‐01 cells were first characterized for ER and ERBB2 protein expression (receptors relevant to the major breast cancer subtypes) by Western blot." (PMID 32667137, 2020). "The combination of USP2 and HSP90 inhibitors effectively restrains ErbB2-positive breast cancer xenograft growth in vivo." (PMID 32327714, 2020).
breast cancer (continued). "The standard adjuvant treatment ERBB2 (formerly HER2 or HER2/neu)-positive breast cancer includes chemotherapy and 1 year of trastuzumab, a recombinant, humanized monoclonal antibody that targets the ERBB2 receptor." (PMID 32833018, 2020). "As expected, ErbB2 expression was downregulated in all breast cancer cell lines tested as revealed by immunoblotting assays using two clones of ErbB2 antibodies." (PMID 32327714, 2020). "Epidermal growth factor receptor 2 (ErbB2) is found overexpressed in several cancers, such as gastric, and breast cancer, and is, therefore, an important therapeutic target." (PMID 32714928, 2020). "The human epidermal growth factor receptor 2 (HER2, also known as ERBB2) is constitutively activated by overexpression or gene amplification in ~15–20% of human breast cancers." (PMID 31462705, 2020). "In particular, EGFR (ErbB1 and HER1) are associated with a variety of solid tumor malignancies and the overexpression of ErbB2 (HER2) is also found in 20–30% of breast cancers." (PMID 33371333, 2020). "To this end, we selected a pilot cohort of 10 patients of 34–60 years of age with metastatic ErbB2-positive breast cancer, nine of which were undergoing trastuzumab-based therapies at the QEII Health Centre in Halifax, NS, during the study." (PMID 33023655, 2020). "34E-7) and the breast cancer biomarker ERBB2 (HER2) (2.77-fold change, p = 0.027) are similar in the same data set." (PMID 33176745, 2020). "Based on findings from the present investigation, we propose a novel therapeutic strategy to treat ErbB2-positive breast cancer via combined pharmacological inhibition of HSP90 and USP2." (PMID 32327714, 2020). "BRCA1 and ERBB2, which play key roles in breast cancer, were significantly correlated with 60 and 43 ATG genes, respectively." (PMID 31896739, 2020). "HER2-positive breast cancer is a subtype of breast cancer and presents an amplification pattern of oncogene HER2 (ERBB2)." (PMID 32570740, 2020). "Depletion and pharmacological suppression of USP2 effectively enhance HSP90 inhibitor-incurred ErbB2 downregulation, as well as significantly deter the in vivo and in vitro growth of ErbB2-positive breast cancer cells." (PMID 32327714, 2020). "One of the best-known cancer amplicons is observed around the ERBB2 locus, at chromosome 17q12, in a subset of breast cancers which become sensitive to treatments specifically targeting the over-expressed HER2 (Human EGFR family Receptor 2) receptor." (PMID 32987805, 2020). "For example, breast cancer cells or mammary epithelial cells over-expressing ERBB2 were more sensitive to the tumor promoting effects of alcohol which suggests that oxidative stress and EGFR/ ERBB2 signaling play an important role in this process." (PMID 33203443, 2020). "ErbB2 is a type of receptor tyrosine kinase normally expressed in epithelial cells, but ErbB2-positive breast cancers are known to express ErbB2 tens of times more than normal cells." (PMID 32599712, 2020). "Drug-induced inhibition of ERRα by C29 in the mouse cell lines NIC-5231 and NIC-5257, derived from ErbB2-driven mammary tumors, also led to a stark reduction in DNMT1 protein." (PMID 32855526, 2020). "ASPM and CMYA5 are predicted as novel oncogenes in breast cancer, while ERBB2 is an already well-known oncogene in breast cancer." (PMID 31900418, 2020). "Trastuzumab, a humanized IgG1 monoclonal antibody targeting Her2, is the standard therapy for Human epidermal growth factor receptor 2 (HER2/Erbb2/neu) overexpressing breast cancer owing to its apparent efficacy in adjuvant and neoadjuvant uses." (PMID 32127568, 2020). "Brain metastasis (BrM) remains a significant cause of cancer-related mortality in epidermal growth factor receptor 2-positive (ERBB2+) breast cancer (BC) patients." (PMID 33019652, 2020).